HSPA8 (heat shock protein family A (Hsp70) member 8)
Diseases named in the same sentence as HSPA8 in open-access papers (continued):
Sharing a sentence is not in itself a finding about the gene and the disease.
atherosclerosis (4 papers, 2016 to 2024). A disease characterized by the build-up of fatty material and calcium deposition in the arterial wall resulting in partial or complete occlusion of the arterial lumen. "The current study thus investigated the association among an HSPA8 SNP, atherosclerosis, and hepatic pathogenesis in NAFLD." (PMID 35886046, 2022). "Members of the stress-inducible heat-shock protein family, including HSPA8, are associated with the development of atherosclerosis and CHD/coronary artery disease (CAD)." (PMID 27790247, 2016). "In the present study, at least one copy of HSPA8 was associated with atherosclerosis in men." (PMID 35886046, 2022). "This work demonstrated that the G allele of the HSPA8 SNP is associated with a higher prevalence of hypertension, greater Max-IMT in male patients, and significant atherosclerosis of the carotid artery in older male patients." (PMID 35886046, 2022). "In contrast to several other heat shock proteins, the upregulation of HSPA8 was shown to have a protective role against atherosclerosis." (PMID 36506940, 2022). "According to the results of the present study, the HSPA8 SNP (rs2236659), at least in part, is a specific marker of atherosclerosis in NAFLD." (PMID 35886046, 2022). "The present study identified the effect of HSPA8 (rs2236659) SNP on atherosclerosis in NAFLD and clarified sex differences and interactions with confounding factors such as liver fibrosis and age." (PMID 35886046, 2022). "In female patients without advanced liver fibrosis, homozygosity for the major A allele of the HSPA8 SNP was associated with nonsignificant atherosclerosis." (PMID 35886046, 2022). "However, to the best of our knowledge, no study has yet investigated the association between HSPA8 SNP and atherosclerosis in NAFLD." (PMID 35886046, 2022). "The genes that were differentially expressed in the lipid and atherosclerosis pathway were APOB (P = 0.008), CD36 (P = 0.040), CALM1, CALM2, CALM3 (P = 0.015), and HSPA8 (P = 0.047)." (PMID 36506940, 2022).
atrial fibrillation (4 papers, 2019 to 2023). A disorder characterized by an electrocardiographic finding of a supraventricular arrhythmia characterized by the replacement of consistent P waves by rapid oscillations or fibrillatory waves that vary in size, shape and timing and are accompanied by an irregular ventricular response. "In rat pulmonary vein cardiomyocytes, HSPA8 can be a helper protein in hyperpolarization activation of chloride ion channels and may be involved in regulating atrial fibrillation." (PMID 38247467, 2023).
chronic myeloid leukemia (4 papers, 2021 to 2024). "HSPA8 is implicated in a signal transduction pathway in the abnormal proliferation of chronic myeloid leukemia (CML) cells, suggesting that the chaperone HSPA8 and CCND1 contribute to the abnormal behavior of CML cells and represent an interesting target for new therapies." (PMID 36284352, 2022). "HSPA8 ablation inhibits cell proliferation and enhances the chemosensitivity of imatinib-resistant chronic myeloid leukemia cells to imatinib." (PMID 38419499, 2024). "Previous studies have reported that HSPA8 can promote BCR/ABL-induced chronic myeloid leukemia cells’ survival." (PMID 33926391, 2021). "Additionally, targeting HSPA8 by downregulating BCR-ABL can enhance the chemotherapy sensitivity of chronic myeloid leukemia cells." (PMID 38420434, 2024).
Cognitive impairment (4 papers, 2020 to 2026). Abnormal cognition is characterized by deficits in thinking, reasoning, or remembering. "Importantly, HSPA8 protein had the highest AUC value for distinguishing between cognitively normal (CN)/mild cognitive impairment (MCI) and MCI/AD groups." (PMID 42052379, 2026).
colitis (4 papers, 2024 to 2025). Inflammation of the colon. "ELNs of edible mulberry bark have been shown to reduce cellular damage associated with colitis by promoting the activation of the heat shock protein family A member 8 (HSPA8)-mediated anti-microbial peptides (AhR) signaling pathway." (PMID 38542448, 2024). "Mulberry bark-derived extracellular vesicles also protect mice from colitis by activating the Aryl hydrocarbon receptor (AhR) signaling pathway mediated by heat shock protein family A member 8 (HSPA8)." (PMID 38545101, 2024).
coronary heart disease (4 papers, 2010 to 2022). "We also performed a proteomic study to reveal PHACTR1 interacting proteins and validated that PHACTR1 can interact with heat shock protein A8 (HSPA8) which was reported to be associated with coronary artery disease and eNOS degradation." (PMID 36091033, 2022). "Genetic variants of HSPA8 gene changed its expression level, which could in turn affect the coronary heart disease (CHD) susceptibility in human." (PMID 35055737, 2022). "HSPA8 genetic variants are associated with the risk of coronary heart disease." (PMID 35886046, 2022). "In addition, another GWAS revealed that HSPA8 genetic variant (SNP rs2236659) is associated with coronary heart disease risk in a Chinese population." (PMID 36091033, 2022).
Hypertension (4 papers, 2020 to 2023). The presence of chronic increased pressure in the systemic arterial system. "In humans, the polymorphisms of HSPA8 gene are significantly associated with the prevalence of hypertension, being hypertension also described in dogs with DM." (PMID 33271797, 2020). "Genetic variations in Hspa8 correlate inversely with the risk of hypertension." (PMID 36760467, 2023). "Some of the modulated proteins in saliva such as HSPA8 or S100A9 have been previously related to DM complications such as hypertension or micro-vascular alterations, while others such as S100A2 and S100A11 are described in DM here for the first time." (PMID 33271797, 2020). "Furthermore, Hspa8 is also upregulated in patients with arterial hypertension, which may be a protective response to EC injury." (PMID 36760467, 2023).
lung adenocarcinoma (4 papers, 2019 to 2026). A carcinoma that arises from the lung and is characterized by the presence of malignant glandular epithelial cells. "Fourth, APCDDD1L-AS1 may promote osimertinib resistance by regulating proteins other than DLST in lung adenocarcinoma, such as HSPA8; however, we did not further explore the mechanism." (PMID 40634956, 2025).
myocardial infarction (4 papers, 2011 to 2025). Gross necrosis of the myocardium, as a result of interruption of the blood supply to the area, as in coronary thrombosis. "Further investigation is needed to fully understand the role of HSPA8 in repairing myocardial infarction." (PMID 38247467, 2023). "More specifically, targeting Hspa8 and Hspa5 has been demonstrated to protect cardiomyocytes and mesenchymal stem cells from hypoxia-induced apoptosis, whereas delivering these heat shock proteins into transplanted mesenchymal stem cells rescues heart function after myocardial infarction in rats." (PMID 21569252, 2011). "Former studies indicated that HSPA8 can interact with aldehyde dehydrogenase 2 (ALDH2) to regulate fibroblast senescence after oxygen–glucose deprivation, providing an option to effectively intervene in fibroblast senescence after myocardial infarction." (PMID 40538098, 2025). "In conclusion, the data from this study suggest that HSPA8, in conjunction with ALDH2, could regulate fibroblast senescence after oxygen-glucose deprivation, providing a new direction and foundation for effectively intervening in fibroblast senescence after myocardial infarction." (PMID 38247467, 2023).
Obesity (4 papers, 2021 to 2024). Accumulation of substantial excess body fat. "However, with obesity, we observed increased accessibility of genes involved in cell cycle regulation (ATM, CDKN1C, BCL2L11), autophagy (HSPA8, IRF8, PEX5), and protein catabolism (CDC34, CTSB, UBB)." (PMID 39872537, 2024).
Cerebral ischemia (3 papers, 2021). Restriction of arterial blood supply to the brain associated with insufficient oxygenation to support the metabolic requirements of the tissue. "In contrast, some research observed that HSPA8 expression was upregulated after cerebral ischemia, and the reduction of HSPA8 contributed to the neurological recovery of the animals." (PMID 34362408, 2021). "Because HSC70 assembles after cerebral ischemia of rats and HSC70 involves diverse proteostasis mechanisms including chaperone mediated autophagy which contributes to oxidative stress response, upregulated HSPA8 coding HSC70 indicated the oxidative stress of our model was existing." (PMID 34168538, 2021).
ischemic stroke (3 papers, 2019 to 2025). A stroke disorder caused by obstruction of blood flow to the brain, due to thrombotic (local blood clot formation) or embolic (due to a blood clot or other material traveling from another site) event. "Here we report the results of the pilot study aimed at determining whether HSPA8 SNPs are linked to the risk of ischemic stroke (IS)." (PMID 37372351, 2023). "The possible significance of HSPA8 (HSC70) in the molecular mechanisms of ischemic stroke has already been noted in previous studies." (PMID 37372351, 2023). "HSPA8 also plays a protective role in the process of ischemic stroke by protection of nerve cells and inhibition of neuronal apoptosis." (PMID 30678657, 2019). "On the other hand, HSPA8 may play a protective role in IS the process of ischemic stroke by protecting nerve cells and inhibiting neuronal apoptosis." (PMID 37372351, 2023).
non-small cell lung carcinoma (3 papers, 2011 to 2021). A group of at least three distinct histological types of lung cancer, including non-small cell squamous cell carcinoma, adenocarcinoma, and large cell carcinoma.
triple-negative breast carcinoma (3 papers, 2021 to 2024). An invasive breast carcinoma which is negative for expression of estrogen receptor (ER), progesterone receptor (PR), and human epidermal growth factor receptor 2 (HER2). "HSPA8 expression is related to TNM staging of triple-negative breast cancer and has important prognostic value." (PMID 38420434, 2024).
active tuberculosis (2 papers, 2022 to 2023). "Suppression of HSPA8 by rifampicin promotes ferroptosis in anti-tuberculosis drug-induced liver injury." (PMID 37715221, 2023).
Ataxia (2 papers, 2017 to 2024). Ataxia refers to impaired coordination of voluntary muscle movement. "Homozygous Hspa8-KI rats exhibited ataxia and axonal spheroids similar to those of F344-kk/kk rats." (PMID 38384479, 2024).
autoimmune disease (2 papers, 2021 to 2023). A disorder resulting from loss of function or tissue destruction of an organ or multiple organs, arising from humoral or cellular immune responses of the individual to their own tissue constituents. "On the one hand, this information brings new ideas for the potential use of the natural products in different pathologies, taking advantage of the multiple functions of HSPA8 in cancer and in autoimmune diseases." (PMID 34586597, 2021).
bladder cancer (2 papers, 2023 to 2024). "The HSPA8‐based risk model can accurately predict gene mutations, survival, clinical features and immune escape in bladder cancer." (PMID 37771276, 2023). "Our study revealed a critical role of HSPA8 or its risk model in bladder cancer growth, metastasis, apoptosis, gene mutations, and the tumour immune microenvironment." (PMID 37771276, 2023). "Our research proved that HSPA8 facilitated metastasis, blocked apoptosis and was linked to a poor prognosis for bladder cancer patients." (PMID 37771276, 2023). "Therefore, this study aims to explore the biological role of HSPA8 in the prognosis of bladder cancer and establish a prognostic risk model based on HSPA8 to predict the overall survival, progression and immune microenvironment of bladder cancer patients." (PMID 37771276, 2023). "Verification of these mechanisms or further exploration of the detailed mechanism of HSPA8 in bladder cancer will be the focus of our next work." (PMID 37771276, 2023). "Heat shock protein member 8 (HSPA8) is one of the most abundant chaperones in eukaryotic cells, but its biological roles in bladder cancer (BC) are largely unclear." (PMID 37771276, 2023). "Notably, all bladder cancer cell lines expressed HSPA8 at high levels, and the expression levels of muscle‐invasive BC cell lines (e.g., T24, UMUC3 and HT‐1197) were significantly higher than those of nonmuscle‐invasive BC cell lines (e.g., RT112 and RT‐4)." (PMID 37771276, 2023). "First, we examined the expression of HSPA8 in bladder cancer cell lines in the HPA database." (PMID 37771276, 2023). "Furthermore, we discovered that overexpression of HSPA8 in the bladder cancer cell lines T24, UMUC3, 5637, and RT112 dramatically reduced the protein expression of caspase‐3." (PMID 37771276, 2023). "HSPA8 is anticipated to be a novel prognostic molecular target for bladder cancer." (PMID 37771276, 2023). "In summary, we indicated that HSPA8 is a potential marker for poor prognosis in bladder cancer." (PMID 37771276, 2023). "Nevertheless, the biological significance of HSPA8 in bladder cancer needs to be clarified." (PMID 37771276, 2023). "However, the biological function of HSPA8 in bladder cancer remains unclear." (PMID 37771276, 2023). "Next, we reduced the amount of HSPA8 expression in the UMUC3 and RT112 cell lines, and the results revealed that bladder cancer cells' capacity for proliferation and migration was dramatically reduced." (PMID 37771276, 2023). "In addition, this study aimed to focus on the biological function of HSPA8 in bladder cancer, and the deep mechanisms of how HSPA8 exerts these biological functions were not revealed in detail." (PMID 37771276, 2023).
cervical cancer (2 papers, 2021 to 2022). A primary or metastatic malignant neoplasm involving the cervix. "Cervical cancer is one of the 5 out of 32 cancers evaluated by TCGA that have significant associations of high HSPA8 mRNA expression with worse survival." (PMID 36203464, 2022). "TCGA data probed with the ualcan.path.uab.edu website shows that cervical cancer does not express higher levels of HSPA8 (gene encoding hsc70) mRNA in comparison to other cancer types." (PMID 36203464, 2022).
cholangiocarcinoma (2 papers, 2022 to 2024). A carcinoma that arises from the intrahepatic biliary tree (intrahepatic cholangiocarcinoma) or from the junction, or adjacent to the junction, of the right and left hepatic ducts (hilar cholangiocarcinoma). "HSPA8 was highly expressed in a variety of cancer, such as BRCA, thyroid cancer, cholangiocarcinoma, liver hepatocellular carcinoma, and colon adenocarcinoma." (PMID 36452344, 2022).
co-infection (2 papers, 2020 to 2021). "Of importance, four gene products, namely, glial fibrillary acidic protein (GFAP), serpin peptidase inhibitor clade A member 3 (SERPINA3), thymidine phosphorylase (TYMP/ECGF1), and heat shock 70 kDA protein 8 (HSPA8), were confirmed to be abundant in TBM patients with HIV coinfection." (PMID 33087432, 2021). "The co-infection allowed observation of multiple genes involved in the obstruction of the viral life cycle within the host such as MX1,MX2, OASL, OAS2, heat shock protein family A (Hsp70) member 8 (HSPA8), and radical S-adenosyl methionine domain containing 2 (RSAD2)." (PMID 33187194, 2020).
epilepsy (2 papers, 2017 to 2021). A brain disorder characterized by episodes of abnormally increased neuronal discharge resulting in transient episodes of sensory or motor neurological dysfunction, or psychic dysfunction. "The fact that Hspa8 is increased only in the DZP group suggests an altered release of neurotransmitters such as GABA and glutamate, but also monoamines, affecting the excitatory imbalance characteristic of epilepsy." (PMID 28758946, 2017).
Hyperglycemia (2 papers, 2018 to 2020). An increased concentration of glucose in the blood. "Our report further supports the functional link of HspA8 to hyperglycemia." (PMID 29867058, 2018).
Hypoglycemia (2 papers, 2021). A decreased concentration of glucose in the blood. "At hypoglycemia, TLR4:MD-2 complex and HSPA8 both decreased in T2D versus baseline (p < 0.05), with HSPA8 remaining significantly lower at hypoglycemia in T2D versus controls (p < 0.01)." (PMID 34831332, 2021). "In the follow-up period after hypoglycemia, HSPA8 remained lower in T2D (p < 0.05), UBE2L3 (p < 0.05) was decreased in controls compared to baseline, and the other HSPs normalized to baseline by 24 h." (PMID 34831332, 2021). "At hypoglycemia, UBE2N, STIP1, and UBE2L3 increased (all p < 0.05), whilst TLR4:MD-2 and HSPA8 decreased (p < 0.05) in T2D versus baseline." (PMID 34831332, 2021). "HSPA8 is part of the HSP70 family and acts as a molecular chaperone; its actions are facilitated by the HSP40 family and, in particular, the DNAJB proteins that, as shown here, were unaffected by hypoglycemia." (PMID 34831332, 2021). "The findings for HSPA8 and HSP90 were similar between severe and mild hypoglycemia." (PMID 34831332, 2021).
Infertility (2 papers, 2017 to 2026). "In other word, these findings indicate the possibility that BPA exposure may lead to the initiations of some latent diseases such as neoplasm and necrosis, together with delayed sex maturation (due to reduced expression of HSPA8) and infertility." (PMID 28928476, 2017).
liver fibrosis (2 papers, 2022 to 2023). "In decision-tree analysis, age, sex, liver fibrosis, and HSPA8 genotype were individually associated with severe carotid artery atherosclerosis (Max-IMT ≥ 1.5 mm)." (PMID 35886046, 2022).
protein misfolding diseases (2 papers, 2017 to 2022). "Several other reports also showed the role of HSPA8 (Hsc70-4 in Drosophila) in the rescue from the proteinopathies in the case of neurodegenerative diseases." (PMID 36425218, 2022).
scrapie (2 papers, 2011 to 2020). A fatal disease of the nervous system in sheep and goats, characterized by pruritus, debility, and locomotor incoordination. "Similarly, autophagy activator genes HSPA8 [heat shock protein family A (Hsp70) member 8] and HSPB8 [heat shock protein family B (small) member 8] are upregulated in the CNS of sCJD-infected Tg340-PRNP129MM mice at clinical stage, sCJD patients, and naturally scrapie-infected sheep." (PMID 32984276, 2020).
Zika virus infection (2 papers, 2020 to 2022). "HSPA8 is a constitutively expressed Hsp70, the most important Hsp70 protein in Zika virus infection." (PMID 35308396, 2022). "We found that HSPA8 depletion by sgRNA1 in U-251 MG cells remarkably attenuated ZIKV infection." (PMID 32753727, 2020).
anemia (1 paper, 2022). A reduction in the number of red blood cells, the amount of hemoglobin, and/or the volume of packed red blood cells. "Based on this evidence, we speculate that HSPA8 may be one of active sites of Roxadustat to act on hematopoietic stem cells to improve the anemia, and may affect glycolysis by regulation of glycolytic genes in hypoxia environment by up-regulating the expression of HSPA8." (PMID 35690731, 2022).
asthma (1 paper, 2022). "Several of these DEGs associated with Tet1 loss in AT2 cells (Il33, Areg and Bpifa1, Hspa8 and Lgals3 (also DEGs in ciliated cells)), have been previously linked to asthma." (PMID 35627266, 2022).
auditory system disease (1 paper, 2022). "As a member of the heat shock protein 70 families, HSPA8 is usually related to auditory system disease and oral lichen planus." (PMID 35855056, 2022).